PKD1 (polycystin 1, transient receptor potential channel interacting)
Diseases named in the same sentence as PKD1 in open-access papers (continued):
Sharing a sentence is not in itself a finding about the gene and the disease.
invasive breast carcinoma (5 papers, 2009 to 2018). A carcinoma that infiltrates the breast parenchyma. "Accordingly, the loss of PKD1 in invasive breast cancer is associated with the loss of Snail phosphorylated at Ser11 leading to induction of EMT as determined by increased expression of N-cadherin and loss of E-cadherin." (PMID 26848698, 2016). "In invasive breast cancer, the loss of PKD1 is mediated by hypermethylation of the PRKD1 promoter." (PMID 26848698, 2016). "PKD1 expression previously has been shown to be downregulated in invasive breast carcinoma through epigenetic silencing of its PRKD1 gene promoter." (PMID 30555634, 2018). "Analyses of patient samples suggest that in invasive breast cancer the downregulation of PKD1 correlates with a decrease of PIP5K1C phosphorylation at S448." (PMID 30555634, 2018). "Loss of PKD1 and upregulation of PKD3 in invasive breast cancer suggests that in this malignancy PKD1 functions as a tumor suppressor while PKD3 functions as an oncoprotein." (PMID 26848698, 2016). "For example, PKD1 is highly-expressed in ductal epithelial cells of the normal breast while its expression is downregulated in highly-invasive breast cancers." (PMID 26848698, 2016). "We further show that decreased expression of PKD1 can serve as a marker for invasive breast cancer, whereas PKD2 and PKD3 expression remain unchanged in normal breast and invasive breast tumour tissue." (PMID 19243594, 2009). "This may appear discrepant with a previous study that identified decreased PKD1 expression as a marker for invasive breast cancer." (PMID 25287328, 2014). "Our results identify decreased expression of the PKD1 as a marker for invasive breast cancer." (PMID 19243594, 2009).
invasive ductal carcinoma (5 papers, 2009 to 2024). "While PKD1 was the dominant isoform in normal breast tissue, samples of invasive ductal carcinoma showed a switch towards PKD3 expression, and a weaker expression of PKD2." (PMID 37293129, 2023). "PIP5K1C phosphorylation at S448 is downregulated in invasive ductal carcinoma, and similarly, the expression levels of PKD1, the kinase that phosphorylates PIP5K1C at this site, are decreased." (PMID 30555634, 2018). "PKD1 expression was downregulated by approximately 60% in more than 95% of the analysed samples of invasive ductal carcinoma and distant lymph node metastases." (PMID 19243594, 2009). "When compared with normal breast tissue the tumour samples revealed an approximate 60% reduction in PKD1 expression in both, invasive ductal carcinoma and metastatic invasive ductal carcinoma." (PMID 19243594, 2009). "Consequently, PKD1 is downregulated in its expression in human invasive ductal carcinoma of the breast." (PMID 22276203, 2012). "In invasive ductal carcinoma of the breast PKD1 is downregulated in its expression." (PMID 22276203, 2012). "We next determined if there is a direct correlation between PKD1 expression and PIP5K1C phosphorylation at S448 in invasive ductal carcinoma." (PMID 30555634, 2018). "Analysis of human tissue samples with a newly-generated phosphospecific antibody for PKD1-phosphorylated SNAI1 showed that regulation of SNAI1 through PKD1 occurs in vivo in normal breast ductal tissue and is decreased or lost in invasive ductal carcinoma." (PMID 22276203, 2012). "In human samples of invasive ductal carcinoma (IDC), PKD1 is downregulated in its expression and activity." (PMID 22276203, 2012). "We analysed TMAs including 10 normal breast tissue samples, 40 invasive ductal carcinoma of the breast and 10 metastatic invasive ductal carcinoma samples from lymph nodes for the expression of the PKD family kinases, PKD1, PKD2 and PKD3." (PMID 19243594, 2009).
melanoma (5 papers, 2017 to 2022). A malignant, usually aggressive tumor composed of atypical, neoplastic melanocytes. "Furthermore, PKD1 expression significantly correlated with the mesenchymal features of the melanoma cell lines used in this study and was associated with a high metastatic potential (anchorage-independent growth and migration)." (PMID 28056869, 2017). "Studies have reported that the expression of ANXA10 is significantly increased in melanoma and can promote melanoma metastasis by suppressing E3 ligase TRIM41-directed PKD1 degradation." (PMID 35693827, 2022). "PKD1 was expressed in 4 out of the 5 melanoma cell lines tested and this expression strongly correlated with E-cadherin negative/N-cadherin positive phenotype and metastatic potential (anchorage-independent growth and migration)." (PMID 28056869, 2017). "In I5, M2 and M4T2 melanoma cells, that express null or very low levels of E-cadherin but high levels of N-cadherin, PKD1 expression was strong with maximal expression in the most aggressive cell line (i.e. M2 cells)." (PMID 28056869, 2017). "To study more specifically and deeply the involvement of PKD1 in melanoma progression, we firstly analyzed the expression pattern of this kinase in different melanoma cell lines." (PMID 28056869, 2017). "PKD1 knockdown in M4T2 metastatic melanoma cells significantly induced down-regulation of N-cadherin and up-regulation of E-cadherin, supporting the role of PKD1 in E-cadherin to N-cadherin switch." (PMID 28056869, 2017). "In T1 and G1 melanoma cells that express high levels of E-cadherin but very low levels of N-cadherin, PKD1 expression was very faint." (PMID 28056869, 2017). "ANXA10 boosts melanoma metastasis via inhibiting E3 ligase TRIM41-directed PKD1 degradation." (PMID 36158697, 2022). "Furthermore, although PKD1 knockdown induced a slight decrease in the horizontal migration (wound healing) potential of metastatic melanoma cells, the inhibition was very low in comparison of the effect of the Gö6976 inhibitor." (PMID 28056869, 2017). "Thus, in some melanoma cells, depending on their protease expression profile, a combinatory inhibition of PKD1 and cPKC might be considered for a more effective reversion of the E- to N-cadherin switch." (PMID 28056869, 2017). "Anchorage-independent growth and migration rates of P5 clone, in which PKD1 expression was only slightly inhibited, were similar to control cells suggesting that a specific and strong PKD1 inhibition is required to revert the metastatic phenotype in melanoma cells." (PMID 28056869, 2017). "Interestingly, in our melanoma progression model, Timp1 was shown to modulate the PI3K/PDK1 axis, since decreased Timp1 expression and PI3K inhibition attenuated PKD1 phosphorylation along with melanoma genesis." (PMID 28430130, 2017). "Since Gö6976 but not Gö6983 induces E-cadherin expression in the E-cadherin-negative metastatic melanoma cells, we tested whether PKD1 depletion would have the same effect." (PMID 28056869, 2017).
Nephropathy (5 papers, 2022 to 2024). A nonspecific term referring to disease or damage of the kidneys. "Eight heterozygous variants were identified in nephropathy-associated genes (CLCN2, C5orf42, GSN, LMX1B, CEP164, PKD1, ITGB4, and KANK2), but each could be discounted having been inherited from an unaffected parent." (PMID 37148394, 2023). "However, despite these signs of kidney damage, BUN was not increased in iKsp‐Pkd1−/− mice." (PMID 38561249, 2024).
Osteopenia (5 papers, 2010 to 2025). Osteopenia is a term to define bone density that is not normal but also not as low as osteoporosis. "We found that this reduction in Pkd1 expression in heterozygous Pkd1+/Δ mice was sufficient to cause osteopenia due to impairment of osteoblast-mediated bone formation and enhanced adipocyte differentiation." (PMID 21151991, 2010). "In addition, Pkd1 deficient mice have an inverse effect on osteoblastic and adipocytic differentiation, such that decreased osteoblastic function and osteopenia were associated with a reciprocal enhancement of adipogensis and increased bone marrow fat." (PMID 25464512, 2014). "Indeed, the selective genetic ablation of Pkd1 in osteoblasts and osteocytes results in osteopenia that is caused by diminished osteoblast-mediated bone formation and increased bone marrow adipogenesis." (PMID 25464512, 2014). "Disruption of Pkd1 in osteoblasts has been shown to reduce bone mineral density, cortical thickness, and trabecular bone volume in mice, contributing to osteopenia and impaired bone formation." (PMID 40235644, 2025). "In this regard, the selective deletion of Pkd1 in osteoblasts by using Osteocalcin(Oc)-Cre and in osteocytes by using Dmp1-Cre results in osteopenia in adult mice because of defects in osteoblast-mediated bone formation." (PMID 23029375, 2012). "Conditional deletion of Pkd1 in osteoblasts using either Osteocalcin(Oc)-Cre or Dmp1-Cre results in defective osteoblast-mediated postnatal bone formation and osteopenia." (PMID 23029375, 2012). "Pkd1 haploinsufficiency (Pkd1+/Δ) resulted in osteopenia, characterized by decreased bone mineral density, trabecular bone volume, and cortical thickness." (PMID 21151991, 2010). "Targeted deletion of Pkd1 in osteoblasts results in osteopenia and abnormalities in Runx2-mediated osteoblast development." (PMID 21151991, 2010). "Moreover, Osteocalcin-Cre mediated conditional deletion of Pkd1 selectively in the osteoblast lineage results in osteopenia due to decreased osteoblast-mediated bone formation." (PMID 21151991, 2010).
polycystic liver disease (5 papers, 2014 to 2025). "Polycystic liver disease (PLD) has been associated with mutations in both the PKD1 and PKD2 genes in patients, and is also observed in genetically engineered mice bearing these mutations." (PMID 25474361, 2014). "In addition, according to whole-exome sequencing of polycystic liver disease (PCLD), in addition to the two most common genes, PRKCHS and SEC63, deletion of the Sec61β gene results in severely reduced expression of polycystin-1, which is encoded by the PKD1 gene." (PMID 40535761, 2025).
Alport syndrome (4 papers, 2023 to 2026). A rare renal disease characterized by glomerular nephropathy with hematuria progressing to end-stage renal disease (ESRD), frequently associated with sensorineural deafness, and occasionally with ocular anomalies. "The case No. 5 of IHK has a compound heterozygous PKD1 genotype, involving a pathogenic and an uncertain significance variant, while the fetus is also heterozygous for a COL4A3 gene variant responsible of the autosomal dominant form of Alport syndrome." (PMID 37662847, 2023).
Aortic dissection (4 papers, 2019 to 2025). Aortic dissection refers to a tear in the intimal layer of the aorta causing a separation between the intima and the medial layers of the aorta. "In recent years, it has been found that some patients with PKD1 gene mutation suffers from aortic dissection." (PMID 33200202, 2020). "Therefore, PKD1 and PKD2 gene abnormalities alone may not fully explain the increased risk of aortic dissection in PKD, warranting further investigation." (PMID 40093803, 2025).
epilepsy (4 papers, 2022 to 2024). A brain disorder characterized by episodes of abnormally increased neuronal discharge resulting in transient episodes of sensory or motor neurological dysfunction, or psychic dysfunction. "This study suggested that PKD1 gene is potentially a candidate pathogenic gene of FS and epilepsy with antecedent FS." (PMID 35620448, 2022). "The evaluation from ClinGen Clinical-Validity Framework also supports a strong association between PKD1 mutations and epilepsy." (PMID 35620448, 2022). "In the present study, compound heterozygous PKD1 mutations were identified in eight unrelated cases with FS and epilepsy with antecedent FS." (PMID 35620448, 2022). "PKD1 compound heterozygous mutations were identified in eight unrelated cases, among which seven probands presented epilepsy with antecedent FS." (PMID 35620448, 2022). "Taken together the data from gene expression profile, gene functions, and PKD1 deficiency animal model, it is suggested that PKD1 was potentially a novel cause of epilepsy." (PMID 35620448, 2022). "Evaluating the clinical validity of PKD1-epilepsy associations based on the framework developed by the clinical genome resource." (PMID 35620448, 2022). "The frequency of the PKD1 variants in the cohort of epilepsy was significantly higher than that in control populations in gnomAD." (PMID 35620448, 2022). "Pkd1 homozygous deficiency is lethal to the mutant mice, and Pkd1 heterozygous mutant mice exhibit quickly inducible epilepsy and hypermyelination, supporting the finding of the epilepsy patient." (PMID 35678678, 2022). "PKD1 gene was potentially a novel causative gene of epilepsy." (PMID 35620448, 2022). "This study aimed to explore the association between PKD1 and epilepsy." (PMID 35620448, 2022). "We reported the case of an infant girl with TSC2/PKD1 contiguous gene syndrome manifesting as epilepsy and early-onset polycystic kidney lesions." (PMID 39323690, 2024). "We evaluated the PKD1-epilepsy correlation by using ClinGen Clinical-Validity Framework." (PMID 35620448, 2022). "In our cohort, a single patient had TSC2/PKD1-CGS and, at 7 months, had epilepsy." (PMID 38671609, 2024).
pancreatic ductal adenocarcinoma (4 papers, 2016 to 2020). An infiltrating adenocarcinoma that arises from the epithelial cells of the pancreas. "Increased expression of PRKD1 and its gene product protein kinase D1 (PKD1) are linked to oncogenic signaling in pancreatic ductal adenocarcinoma, but a direct functional relationship to oncogenic KRas has not been established so far." (PMID 27649783, 2016). "Valproic acid targeting HDAC9, a known interactor of PKD1, restores ciliogenesis in pancreatic ductal adenocarcinoma cells." (PMID 32973177, 2020). "PKD1 has been shown to be upregulated both in expression and activity in pancreatic ductal adenocarcinoma as compared to normal pancreatic ducts." (PMID 30419840, 2018). "PKD1 expression was detected in human pancreatic intraepithelial neoplasia lesions (MCS = 12.9; P < 0.0001) and pancreatic ductal adenocarcinoma samples (MCS = 15, P < 0.0001) as compared with faint or no expression in normal pancreatic tissues (MCS = 1.54; P < 0.0001)." (PMID 31819177, 2020).
skin cancer (4 papers, 2015 to 2021). "In certain cancers including pancreatic and skin cancer, higher PKD1 expression and activity were detected in tumors as compared to normal tissues and increased PKD1 expression was associated with hyper-proliferative phenotype and increased tumor aggressiveness." (PMID 30419840, 2018). "In skin cancer, increased PKD1 expression has been demonstrated in basal cell carcinoma lesions as compared to normal epidermis." (PMID 30419840, 2018). "This variant is therefore expected to perturb signaling downstream of PKD1, a kinase with roles in the development and metastatic progression of several cancers including prostate, breast, gastrointestinal, pancreatic, and skin cancers." (PMID 26388441, 2015). "However, when the dorsal skin was wounded, PKD1-knockout mice displayed delayed wound re-epithelialization, reduced proliferation, and migration of keratinocytes at the wound edge compared to the control mice, implying a potential critical pro-proliferative role for PKD1 in skin carcinoma." (PMID 33807058, 2021). "Furthermore, PKD1 was found to be strongly expressed in CD34(+) cells and that inhibition of PKD1 could be preventive in skin cancer development." (PMID 26148697, 2015).
angiomyolipoma (3 papers, 2015 to 2023). A neoplasm with perivascular epithelioid cell differentiation often associated with tuberous sclerosis. "None of the patients in the EXIST-2 angiomyolipoma trial had large genomic deletions extending into the PKD1 gene." (PMID 25782670, 2015).
atherosclerosis (3 papers, 2019 to 2025). A disease characterized by the build-up of fatty material and calcium deposition in the arterial wall resulting in partial or complete occlusion of the arterial lumen. "The present study provides evidence that H19 recruits CTCF to downregulate the expression of PKD1, thereby promoting vulnerable plaque formation and intraplaque angiogenesis in mice with atherosclerosis." (PMID 31757932, 2019). "H19 was capable of recruiting CTCF to suppress PKD1, thus promoting atherosclerotic vulnerable plaque formation and intraplaque angiogenesis in atherosclerosis mice." (PMID 31757932, 2019). "This study aimed to explore the interactions among long non-coding RNA H19, transcriptional factor CCCTC-binding factor (CTCF) and polycystic kidney disease 1 (PKD1), and to investigate its potentially regulatory effect on vulnerable plaque formation and angiogenesis of atherosclerosis." (PMID 31757932, 2019).